INS (insulin)
Diseases named in the same sentence as INS in open-access papers (continued):
Sharing a sentence is not in itself a finding about the gene and the disease.
diabetes (continued). "Insulin therapy is a standard treatment for diabetes to restore glucose homeostasis; however, this therapy is associated with increased maternal weight gain and hypoglycaemia." (PMID 34071182, 2021). "We also analyzed the change of A1c level with respect to sex, race, type of diabetes, type of insurance, and mode of insulin administration, using a 2-sample t-test." (PMID 34020722, 2021). "Type 1 diabetes (T1DM), which represents only about five percent of diabetes mellitus cases, results from the progressive destruction of pancreatic beta-cells and consequent inability to produce insulin." (PMID 35211087, 2021). "Diabetes occurs as a result of insufficient production of insulin or insufficient use of produced insulin." (PMID 34194538, 2021). "The pre-diabetes stage is considered to present progressive resistance to insulin, being offset by insulin hypersecretion by beta-cells, resulting in maintaining plasma glucose levels within the pre-diabetes limits." (PMID 34659123, 2021). "Administration of insulin reduced concentrations of α1-acid glycoprotein and restored neutrophil migration in a rodent model of sepsis and alloxan induced diabetes in vivo." (PMID 34149714, 2021). "Increased expression of glucokinase and insulin in the beta-cells of diabetes-prone mice supplemented with high-dose biotin indicates that a protective effect of biotin on beta cell function in diabetic or pre-diabetic rodents." (PMID 35052168, 2021). "Diabetes is a metabolic disorder characterized by hyperglycemia, which results from a decrease in insulin secretion, a decrease in the cells' response to insulin, or both." (PMID 33980300, 2021). "A three-fold mechanism of proper diet, insulin intervention and physical activity for management of diabetes and slowing down the prevalence of the disease is need of the hour." (PMID 34360135, 2021). "Cer is also involved in the mechanism of diabetes by regulating the insulin signaling pathway as a second messenger." (PMID 34547287, 2021). "Effect sizes were similar between all diabetes in pregnancy groups: insulin (12 studies n = 2345), glyburide (4 studies n = 525)." (PMID 33927270, 2021). "The clinical relevance of ETV5 as a CRL4COP1-degradable checkpoint in feeding-induced insulin secretion is underscored by GWAS identification of ETV5 as a diabetes/obesity-related gene." (PMID 33911083, 2021). "The dysregulation of autophagy-related mechanisms after diabetes can lead to a decrease in the number of pancreatic β-cells and dysfunction, resulting in a decrease in insulin secretion." (PMID 34987478, 2021). "Diabetes was induced by a single injection of streptozotocin, and diabetic treated group also received insulin." (PMID 34060586, 2021). "For example, several randomized controlled trials have indicated that standardized fecal bacterial transplantation can reduce insulin resistance and improve insulin sensitivity, halting the progression of diabetes." (PMID 33816351, 2021). "This cross-sectional study evaluated factors that influenced symptoms of injection site infection among 238 Japanese patients who self-injected insulin for diabetes between October 2015 and January 2016." (PMID 33916158, 2021). "These bacteria ferment dietary fibers to produce butyrate through gut microbial metabolism, thus playing a regulatory role in improving insulin sensitivity, alleviating inflammation, and ameliorating diabetes in humans and mice." (PMID 33816351, 2021). "Linagliptin is a dipeptidyl peptidase-4 inhibitor that reduces blood sugar by increasing insulin and decreasing glucagon production by the pancreas, used to treat diabetes mellitus type 2." (PMID 33525510, 2021). "The literature review suggests that in diabetes, dysfunction of insulin and altered GSK-3β signaling in the brain contribute to the tau hyperphosphorylation, thereby potentially increasing the risk of developing AD." (PMID 34725612, 2021).
diabetes (continued). "Diabetes mellitus is one of the most common metabolic disorders due to lack of insulin production or the inability to control blood glucose by insulin leading to hyperglycemia." (PMID 34607602, 2021). "This compound demonstrated potential use to develop agents for diabetes treatment due to the pronounced glucose uptake effect on liver HepG2 cells under normal and insulin-resistant conditions." (PMID 34356949, 2021). "Diabetes laboratory testing was frequently unavailable, and traveling to the district health office to obtain insulin, after attending primary care, remains a difficult cycle for the patient to achieve." (PMID 33777712, 2021). "Hypoglycemia is also a problem in diabetic patients using insulin replacement therapy; in particular severe hypoglycemia can lead to death in type 1 diabetes mellitus." (PMID 33428669, 2021). "Diabetes is a disease that requires self-management that includes lifestyle modifications, self-monitoring of blood glucose as well as adjustment of insulin dosage." (PMID 35002492, 2021). "Diabetes involves various cellular pathways such as insulin secretion, insulin resistance, and carbohydrate absorption." (PMID 34641501, 2021). "Diabetes mellitus occurs when β-cells fail to secrete the insulin necessary to maintain the homeostasis of glucose in the blood." (PMID 34987478, 2021). "A few studies conducted on chicory leaves extracts suggest that chicory leaves are efficient in managing diabetes due to their ability to improve glucose metabolism and the serum insulin level." (PMID 33498684, 2021). "CSII appears to be an effective option for intensive insulin therapy in people with diabetes for improving suboptimal glycaemic control." (PMID 33686483, 2021). "Type 2 diabetes mellitus (T2DM), accounting for around 90% of diabetes cases, is characterized by high insulin resistance and inadequate insulin production, resulting in high glycemic levels." (PMID 35056371, 2021). "Noteworthy, increased levels of serum insulin are typically detected in subjects with pre-diabetes and T2D." (PMID 34243726, 2021). "Diabetes mellitus is a disease wherein carbohydrates, lipids, and proteins are metabolized aberrantly due to the insufficient secretion and action of insulin." (PMID 34681566, 2021). "In our study, the high-risk population for developing pneumonia, namely patients with type 2 diabetes mellitus undergoing insulin therapy, had a lower mean age compared to the control group but had a higher rate of comorbidities when compared to the controls." (PMID 34683125, 2021). "The abnormally high concentration of plasma lipids in diabetes is mainly due to the increased mobilization of free fatty acids from peripheral deposits, as insulin inhibits hormone-sensitive lipase (Garg, 1994 ▶)." (PMID 34290966, 2021). "Overall the raised levels of these pro-inflammatory cytokines in hepatocytes, muscle, and adipose tissue play a major role in the pathology of diabetes by interfering with insulin signalling and inducing insulin resistance." (PMID 33575913, 2021). "More than half of all programs administer a CHO-containing beverage to patients with diabetes, and surprisingly, there is significant use of simple carbohydrate beverages in patients with diabetes receiving insulin." (PMID 34044894, 2021). "Although we found no superior performance of machine learning over logistic regression, machine learning had higher accuracy in the prediction of insulin initiation than general physicians, defined by diabetes specialists’ choice of the gold standard." (PMID 33502325, 2021). "Hypoglycemia occurs frequently in patients with diabetes treated with insulin and/or insulin secretagogues." (PMID 34744863, 2021). "In patients with RI or diabetes, a defect in the regulatory capacity of insulin on ApoB secretion has been demonstrated, leading to increased VLDL release." (PMID 33801107, 2021).
diabetes (continued). "Type 1 diabetes mellitus (T1D) is an autoimmune disorder disease involving the specific destruction of insulin-producing pancreatic beta cells." (PMID 33868170, 2021). "In 1922, Leonard Thompson became the first person to receive insulin therapy for diabetes, and shortly thereafter commercial production and wide-spread use of life-saving insulin began." (PMID 34822454, 2021). "Failure of insulin action is a characteristic of type 2 diabetes and also known as non-insulin-dependent diabetes mellitus (NIDDM)." (PMID 33996978, 2021). "Understanding signaling pathways that regulate pancreatic β-cell function to produce, store, and release insulin, as well as pathways that control β-cell proliferation, is vital to find new treatments for diabetes mellitus." (PMID 34582892, 2021). "Type 1 diabetes mellitus (T1DM) is insulin dependent and caused by the inability of the pancreatic beta cells to synthesize insulin, accounted for by the autoimmune destruction of beta cells." (PMID 34225729, 2021). "Inhibit the diabetes development and the promoting effects of miR-657 on inflammatory cytokine production.Increase insulin sensitive." (PMID 34248996, 2021). "Features key to the existence of a well-rounded diabetes management program were included and assessed in this study: blood glucose A1C, insulin, physical activity, and prescription medication." (PMID 34463627, 2021). "Multiple AMPK activators, such as A769662 and the widely used diabetes medication metformin, have been reported to inhibit hepatic lipogenesis, suppress glucose production, and improve insulin sensitivity." (PMID 34671010, 2021). "Advances in diabetes technologies over the past decade have provided cost-effective and valuable tools to safely commence insulin therapy and manage the disease effectively." (PMID 33950566, 2021). "Diabetes is a metabolic disorder stemming from defective insulin secretion and the occurrence of insulin resistance in peripheral tissues." (PMID 34959658, 2021). "As overt obesity and inflammation of adipose stores are prognostic markers for diabetes development, we tested the glucose and insulin tolerance of the Mdm2Adi+/− mice." (PMID 34750429, 2021). "Like type 1 diabetes, diabetes-induced by PD-1 inhibitors should receive long-term insulin treatment after remission of DKA." (PMID 34106616, 2021). "Patients with diabetes mellitus have a lower incidence of prostate cancer due to low androgen, insulin, and IGF-1 levels." (PMID 33921222, 2021). "Although advances have been made in techniques (e.g., insulin analogues) and evidence-based diabetes management, FoH remains a problem in diabetes management." (PMID 33846441, 2021). "The measuring, recording, and sharing of SMBG practices in patients with diabetes using insulin were investigated." (PMID 34704954, 2021). "Diabetes can be defined as a heterogeneous aetio-pathology that includes defects in insulin secretion, insulin action, or both, and disturbances of carbohydrate, fat, and protein metabolism." (PMID 34439425, 2021). "SDM became crucial in PHC because, through this method, patients with diabetes have an opportunity to choose either insulin injection or oral drugs for glucose control; furthermore, health professionals must discuss the best suitable treatment with patients." (PMID 34204428, 2021). "Up-regulated genes were also strong enriched in lipid metabolism pathways, which has been shown to regulate insulin secretion and contribute to diabetes." (PMID 33983929, 2021). "Most type 2 diabetes mellitus (T2DM) patients need exogenous insulin therapy during clinical treatment; therefore, their serum insulin levels are higher compared with non-diabetic people." (PMID 34034636, 2021). "An adaptation of ACT content for diabetes involved incorporating behaviours relevant to diabetes adherence (mindful eating, exercising, glucose monitoring and administering insulin injections) into a generic creative hopelessness ACT exercise." (PMID 34775953, 2021).
diabetes (continued). "The purpose of this study is to explore FHL levels and numeracy skills in an insulin-treated T2DM patient population are related to diabetes, and they impact on diabetes therapy." (PMID 33561956, 2021). "Insulin analogs and their biosimilars are commonly used for the treatment of patients with diabetes; therefore, their safety and efficacy should be noticed." (PMID 34925042, 2021). "Diabetes mellitus is a chronic metabolic disorder resulting from insufficient active insulin or abnormal response to insulin, and leading to high levels of blood glucose (hyperglycemia)." (PMID 34502417, 2021). "Though diabetes is fundamentally a disease of the pancreas, specifically of the beta cells and of insulin dysfunction, the possible complications resulting from the disease are far-reaching." (PMID 34368082, 2021). "The obesity-related comorbidities are hypertension, reduced insulin sensitivity, diabetes mellitus, some types of cancer, and various heart diseases." (PMID 33800151, 2021). "In this study, we systematically investigated the anti-DR properties of BBR in insulin-treated diabetes." (PMID 34803500, 2021). "Herein, we demonstrated that that minocycline at physiological concentrations induced degradation of insulin amyloids formed from human insulin and insulin drug preparations used for diabetes patients." (PMID 33767265, 2021). "Diabetes mellitus (DM), a chronic metabolic disorder characterized by hyperglycemia resulting from increased hepatic glucose production, impaired insulin production by pancreatic β cells and insulin resistance." (PMID 34725640, 2021). "Diabetes mellitus is a high‐incidence chronic disease, which is characterized by high blood glucose levels, low body weights, and insulin secretion increase." (PMID 34026064, 2021). "In rats with streptozotocin-induced diabetes, insulin has been reported to protect retinal function, reducing retinal cell apoptosis, glial activation, VEGF upregulation, and Brain-Retinal-Barrier damage." (PMID 34912295, 2021). "Insulin resistance (IR) is one of the essential conditions in the development of type 2 diabetes mellitus, and insulin reduces blood sugar levels and improves IR by promoting glucose absorption." (PMID 34770958, 2021). "Complementing these guidelines, Chavez and colleagues stated that physical activity, nutrition, blood glucose testing, medication or insulin dosage, health feedback, and education were key diabetes management tasks." (PMID 35010385, 2021). "Type 1 diabetes mellitus (T1DM) is a chronic autoimmune disease that results in elevated blood glucose levels due to destruction of insulin-producing pancreatic islet β cells." (PMID 33528374, 2021). "All the animal studies were performed on T1D models (alloxan or streptozotocin induced rodents), and a further work used an insulin-resistant HepG2 cell model, which is a human hepatocellular carcinoma cell line often used in diabetes research." (PMID 34359462, 2021). "FGF1 was regarded as a potential weapon for treating diabetes because of its excellent blood glucose control and insulin sensitization effects." (PMID 33788387, 2021). "Knockout mice for MafA develop glucose intolerance and diabetes, lower expression of the insulin gene, PDX-1, NeuroD and GLUT2." (PMID 34638652, 2021). "The earlier code for type 2 DM focuses mainly on the code for the long-term use of insulin within the same visit, but the later diabetes code focuses on the insulin code, both in the current and the previous visits." (PMID 34017034, 2021). "Insulin injection technique re-education and diabetes knowledge empowerment has led to improved glycemic control." (PMID 34400860, 2021). "Overall, biocompatible MVLs offer a promising strategy for glucose-responsive insulin delivery and provide an effective approach for the management of diabetes." (PMID 35056918, 2021).
diabetes (continued). "Since the early discovery of insulin, numerous antihyperglycemic drug therapies to treat diabetes have been approved, and also discontinued, by the United States Food and Drug Administration (FDA)." (PMID 35126141, 2021). "Type 2 diabetes mellitus is a metabolic disorder marked by the rise in blood glucose due to a decrease in insulin secretion by pancreatic β-cells and insulin resistance." (PMID 34745425, 2021). "Educational methods utilised included sessions for junior doctors to improve safety of prescribing, insulin specific teaching by the diabetes team, and inclusion of insulin safety content within organisational medication safety newsletters." (PMID 33807829, 2021). "Compared to those with normal BMI, individuals with T1DM and overweight/obesity had longer diabetes duration; higher total daily insulin dose; and higher DD prevalence: 48/57 (84.2 %) vs. 14/50 (28 %) (p < 0.01); with similar HbA1c." (PMID 34530819, 2021). "Diabetes mellitus is a heterogeneous disease characterized by hyperglycemia due to impaired insulin secretion and/or action." (PMID 34681954, 2021). "In the EXPLODE study, we will test the acceptability of one resistance exercise training programme, and gather data on how the programme influences the health of older people with insulin treated diabetes." (PMID 34880011, 2021). "Most participants were familiar with diabetes technologies: 82.7% used insulin pumps and 86.6% routinely used CGM." (PMID 34277978, 2021). "The study group consisted of 38 children with T1D aged < 7 years (34% aged 2–4, 66% aged 5–7 years), HbA1c: 6.53 ± 0.63%, duration of diabetes: 2.6 ± 1.6 years, treated with an rtCGM-augmented insulin pump for 1.92 ± 1.15 years." (PMID 34070638, 2021). "Patients with this type of diabetes require insulin therapy to maintain normoglycemia and a healthy lifestyle to manage their condition effectively." (PMID 33467194, 2021). "SIRT6 also regulates crucial proteins involved insugar homeostasis,as it promotes the expression of glycolytic genes, suppressing gluconeogenesis and increasing insulin secretion, hencehaving a favorable role in diabetes." (PMID 34213345, 2021). "A recent meta-analysis of miRNA expression profiles of patients with type 2 diabetes or rodent models of diabetes identified miR-29a as the most upregulated miRNA across different insulin-sensitive tissues." (PMID 33938394, 2021). "Eventually, these mice develop advanced diabetes with a deteriorated β-cell insulin secretion by the 20th week." (PMID 34764278, 2021). "The fact that patients were on insulin reflect that they are either type 1 or uncontrolled type 2 diabetes mellitus." (PMID 34949164, 2021). "During the progression of diabetes, β-cells expand in size and number to meet the high metabolic demand imposed by insulin resistance." (PMID 33483593, 2021). "These unmet needs have led to the ongoing search for developing insulin pens that can address these errors and provide more efficacious and safer choices for patients with diabetes." (PMID 34924015, 2021). "Our study is to summarize the effects of insulin therapy and clinical in outcomes of patients with COVID-19 and diabetes." (PMID 34367067, 2021). "It has been well documented that APN is an insulin sensitizer, and plays an important role in the pathogenesis of IR, diabetes, and metabolic disease." (PMID 34867822, 2021). "A promising strategy to restore insulin secretion in diabetes mellitus is the transplantation of pancreatic islets." (PMID 34578651, 2021). "Since 2009, several expert group recommendations and evidence-based guidelines on the various aspects of use of insulin in individuals with diabetes mellitus have been published in India." (PMID 34071359, 2021). "A total of 14 patients required insulin for their diabetes control, either as primary treatment for T1DM (11 patients) or for add on therapy for T2DM (three patients)." (PMID 34957200, 2021).